ADIPOR1 (adiponectin receptor 1)
Diseases named in the same sentence as ADIPOR1 in open-access papers (continued):
Sharing a sentence is not in itself a finding about the gene and the disease.
diabetes (46 papers, 2008 to 2026). "We then validated the protein expression of AdipoR1 and AdipoR2 in murine and cellular models of diabetes." (PMID 41146365, 2025). "Previous studies have shown that the expression of both adiponectin and AdipoR1 is increased in the retinas of patients with diabetes." (PMID 38166990, 2024). "The AdipoR1/2 proteins are often discussed in the context of diabetes due to their ability to promote insulin sensitivity and oppose hepatic steatosis." (PMID 36418331, 2022). "AdipoRon treatment restored the diabetes-induced decreases in intracardiac AdipoR1 and AdipoR2 expressions to levels comparable to those in control db/m mice." (PMID 35351872, 2022). "In summary, our study identified that nicotine-provoked SOCS3-mediated AdipoR1 ubiquitination is a key mechanism of APN resistance in diabetes with nicotine." (PMID 34006831, 2021). "This echoes results reported in a previous study proposing that increased insulin sensitivity upon AdipoRon treatment can restore diabetes-induced decrease in renal and cardiac AdipoR1 and AdipoR2 expression to the levels present in control db/m mice." (PMID 34214600, 2021). "Our study revealed for the first time that AdipoRon treatment can ameliorate diabetes-induced tubular injury by regulating ER stress and that this effect occurs partially through the AdipoR1/p-AMPK pathway." (PMID 32832003, 2020). "Both mitochondrial dysfunction and impaired adiponectin/AdipoR1 signaling are thought to contribute to tissue damage in diabetes complication organs, including diabetic cardiomyopathy, diabetic nephropathy and non-alcoholic fatty liver disease." (PMID 31920982, 2019). "AdipoR1 mice were then mated with Akita mice, a diabetes model in which β-cell apoptosis results from endoplasmic reticulum (ER) stress." (PMID 29304075, 2018). "Previous studies demonstrated that resveratrol alleviated alcoholic fatty liver disease in mice by increasing hepatic AdipoR1/R2 expression and attenuated DN by increasing renal AdipoR1 expression in rats with streptozotocin-induced diabetes." (PMID 27286657, 2016). "Compared with the control group, adiponectin, adipoR1, and adipoR2 showed significantly increased protein expression levels in the diabetes group (P < 0.05 for adipoR1 and adipoR2 and P < 0.001 for adiponectin)." (PMID 25525608, 2014). "The expression of cardiac AdipoR1 was increased in the early stage of rat diabetes compared with control rats, which was similar to the findings observed in the late stage (8-weeks) of STZ-diabetic models." (PMID 21912612, 2011). "It is possible that AdipoR1 activation plays a dominant role in APN mediated AMPK-α activation in early diabetes." (PMID 21912612, 2011). "Similarly, AdipoR1 mRNA was also increased in the skeletal muscle of T2D db/db obese and Lepr–/–mice, in which the overexpression of AdipoR1 prevented diabetes by improving insulin sensitivity." (PMID 35055468, 2022). "To investigate whether THC restores adiponectin-mediated function in the pancreas in diabetes, we examined AdipoR1 and APPL1 levels with immunofluorescence staining." (PMID 34960104, 2021). "The pattern of AdipoR1 fragmentation and autoantibody production under physiological conditions of aging, DIO, and autoimmune diabetes therefore provides insight into the association adiponectin biology and diabetes." (PMID 34414399, 2020). "In this regard, we hypothesized that AdipoRon protects against diabetes-induced ER stress possibly through the AdipoR1/p-AMPK signaling pathway." (PMID 32832003, 2020). "Using Adipor1−/− mice, we performed comparative mitochondrial proteomics in cardiac, renal, and hepatic tissues to evaluate potential relative contributions of impaired AdipoR1-mediated adiponectin signaling to diabetes-induced mitochondrial defects and proteomic remodeling." (PMID 31920982, 2019).
diabetes (continued). "Studying the C. elegans homologs of the anti-diabetic adiponectin receptors (AdipoR1 and AdipoR2) has led us to exciting new discoveries and to revisit what may be termed “The Membrane Theory of Diabetes”." (PMID 27671740, 2016). "In addition, decreases in the expression of AdipoR1 and AdipoR2 were observed in people with a family history of type 2 diabetes mellitus and the expression levels of both receptors correlated positively with insulin sensitivity." (PMID 28721260, 2015). "Evaluating the expression of AdipoR1/R2 in single-cell pancreatic islet RNAseq datasets related to Early and Late Diabetes mellitus (DM) offers a promising avenue for researchers to gain deeper insights into the potential role of APN/AdipoRs signaling in DM." (PMID 38004353, 2023). "miR-204 upregulation, reduced NOX, RAGE, MMPs expression, downregulation of IKKβ/NF-κB phosphorylation, Nrf2, AdipoR1/2, JNK activation, TNF-α and IL-6, reduced macrophage infiltration, and ERK and PDX1 activation may reduce diabetes-associated CVDs and diabetic nephropathy." (PMID 37108833, 2023). "Pioglitazone (PIO), a diabetes drug, improves the effect of insulin/leptin in the hypothalamus, partly by activating the Adipo/AdipoR1/AMPK axis in the hypothalamus, suggesting that Adipo and AdipoR1 may play an important role in improving the effect of IR in hypothalamus." (PMID 37034166, 2023). "Furthermore, the effects of AdipoRon were also partially abolished by cotreatment with compound C. Together, these results suggest that AdipoRon exerts favorable effects on diabetes-induced tubular injury in DN by inhibiting ER stress mediated by the AdipoR1/p-AMPK pathway." (PMID 32832003, 2020). "Maintaining AdipoR1 signaling, e.g., by pharmacological activation of AdipoRs using AdipoRon, may represent a useful approach to delay or attenuate the development of specific features observed in diabetes complication organs." (PMID 31920982, 2019). "In this study, we observed that AdipoRon restored the expression of AdipoR1 in DN, along with an apparent increase in AMPK phosphorylation, thereby attenuating diabetes-induced ER stress, inflammation, apoptosis, and fibrosis in the tubules of DN." (PMID 32832003, 2020). "In summary, we identified a diabetes-specific QTL on chromosome 1 at 242 cM for weight in American Indians, in the region where the ADIPOR1 gene is located." (PMID 18854016, 2008). "Our findings offer dual strategies: repurposing AdipoR1 agonists (e.g., AdipoRon) or reducing circulating KAL (e.g., via genetic ablation or triglyceride-lowering agents such as fenofibrate), both applicable to diabetes/MASLD-related metabolic myopathy." (PMID 41922933, 2026). "Second, based upon the analysis above, as the mRNA levels of APN and AdpoR1 are highly elevated in diabetic retina, APN may be actively transported through the BRB into the retina by AdipoR1." (PMID 23922494, 2013). "The increased cardiac protein expression of AdipoR1 in diabetic rats may be a compensatory mechanism in response to decreased plasma and cardiac APN in the early stage of diabetes." (PMID 21912612, 2011). "For instance, pharmacological activation of AdipoR1/2 as nicely ilustrated in8,15 could be exploited to treat pathologies that correlate with abnormally elevated levels of SFA in phospholipids and membrane properties changes, such as diabetes (reviewed in59)." (PMID 36418331, 2022).
breast carcinoma (38 papers, 2008 to 2026). "We showed that two functional polymorphisms of ADIPOQ, and one functional polymorphism which has been shown to alter mRNA levels of ADIPOR1 was significantly associated with risk of breast cancer." (PMID 22295251, 2012). "Additionally, previous research has confirmed the roles of these five central genes (CEACAM6, CAMP, PNPLA2, OLR1, and ADIPOR1) in breast cancer, which were consistent with our predictions of risk and protective factors." (PMID 40282270, 2025). "In addition, women who carried effect alleles in ADIPOR1 rs2232853 (T/C) were associated with increased risk of breast cancer in a case-control study that consists of predominantly White women aged 20 to 87 years." (PMID 34367982, 2021). "High mRNA levels of ADIPOR1 have earlier been associated with lower risk of breast cancer." (PMID 20553615, 2010). "Adiponectin has been found to directly regulate the growth of normal breast epithelial cells and breast cancer cells through the ADIPOR1 and ADIPOR2 receptors." (PMID 40080350, 2025). "To validate the role of AdipoR1/2 in breast cancer cell viability, we conducted MTT assays in the three cell lines." (PMID 37454080, 2023). "ADIPOR1 protein was dysregulated in breast cancer, clear cell renal cell carcinoma, glioblastoma multiforme, head and neck squamous carcinoma, hepatocellular carcinoma, and lung adenocarcinoma." (PMID 36896172, 2023). "Further studies utilizing animal models and clinical trials are needed to validate the efficacy of AdipoR1/2 as therapeutic targets and to explore their potential use in breast cancer treatment." (PMID 37454080, 2023). "We analysed samples from 113 preoperative breast cancer patients and performed IHC to evaluate the level of AdipoR1 and AdipoR2." (PMID 37454080, 2023). "Particularly, the low adiponectin serum levels upregulate AdipoR1 expression in breast cancer tissue as a kind of feedback loop." (PMID 37240258, 2023). "The tumor with the highest frequency of ADIPOR1 alteration is breast cancer, while the tumor with the highest frequency of ADIPOR2 alteration is ovarian epithelial tumor." (PMID 36896172, 2023). "AdipoR1 and AdiporR2 are also found to be enriched in the dendritic cells (DCs) from patients with metastatic or locally advanced breast cancer." (PMID 36896172, 2023). "Emphatically, knockdown of adiponectin receptor 1 (AdipoR1) and AdipoR2 impaired the proliferation and invasion of breast cancer cells." (PMID 37454080, 2023). "After classifying women according to BMI, they described that overweight or obese women have lower adiponectin expression but higher ADIPOR1 expression in breast cancer tissue than in women with normal BMI, contrary to our findings." (PMID 35627631, 2022). "There are two adiponectin receptor subtypes, AdipoR1 and AdipoR2, which have been identified in mammalian tissues, including human cancer cell lines and also in human mammary tumors." (PMID 32215366, 2019). "Indistinctly of the molecular classification of breast cancer of the cell lines used, they all express leptin, adiponectin, AdipoR1, and AdipoR2." (PMID 29311755, 2017). "Independently of the adipose contribution to breast cancer growth, there exists a distinct benefit of stabilizing AdipoR1 signaling in breast cancer cells." (PMID 28676553, 2017). "Epithelial-mesenchymal transition (EMT) in breast cancer is aberrantly activated by overexpression of miRNA-221 and miRNA-222, which target adiponectin receptor 1 (ADIPOR1)." (PMID 29383201, 2017). "As for the expression assay, in MCF-7 breast cancer cells, the expression of mRNA of AdipoR2 (2.423 ± 2.35) was greater than the expression of AdipoR1 (1.679 ± 1.76)." (PMID 29311755, 2017). "Hwang and colleagues found that miR-221/222 targets adiponectin receptor 1 to promote the epithelial-to-mesenchymal transition in breast cancer." (PMID 25078265, 2014).
breast carcinoma (continued). "We conclude that ADIPOR1 negatively regulates EMT in breast cancer and provides an additional node by which miR-221/222 induces the EMT." (PMID 23776679, 2013). "To further confirm ADIPOR1 as a regulator of the EMT in breast cancer cell lines, we sought to overexpress the receptor." (PMID 23776679, 2013). "ADIPOR1 is expressed at higher levels in the luminal compared to the basal-like subtype of breast cancer cell lines, which can be reduced by miR-221/222 targeting of its 3’UTR." (PMID 23776679, 2013). "Together, these data suggest that ADIPOR1 abundance in the luminal-subtype of breast cancers protects against the EMT, and this protection can be conferred by overexpression in the basal-like subtype." (PMID 23776679, 2013). "Some previous reports suggested that cytostatic effects of adiponectin in breast cancer cells are primarily mediated through AdipoR1, and our results with AdipoR2-negative cells and AdipoR2-knockdown cells confirm this notion." (PMID 21974986, 2011). "AdipoR1 appears to play a more definite role in breast cancer, as adiponectin-dependent antiproliferative effects are abolished by siRNA knockdown of this receptor." (PMID 21974986, 2011). "We have been able to show that five different breast cancer cell lines express either AdipoR1 and/or AdipoR2 protein." (PMID 18182989, 2008). "AdipoR1 was most frequently amplified and overexpressed in breast cancer across molecular subtypes." (PMID 41888104, 2026). "Finally, we will further explore the signaling pathways by which ADIPOR1/2 promotes breast cancer to better understand the impact of adipocytes on breast cancer." (PMID 37454080, 2023). "We then investigated the effect of AdipoR1/2 on the invasiveness of breast cancer cells." (PMID 37454080, 2023). "Therefore, further research and exploration are necessary to fully understand the role of ADIPOQ and AdipoR1/2 in breast cancer." (PMID 37454080, 2023). "However, AdipoR1 can regulate EMT in breast cancer as a direct target of microRNAs (miRNAs) miR-221 and miR-222 (miR-221/222) and provides an additional node by which miR-221/222 induces BCCs EMT." (PMID 37686525, 2023). "A more specific biological pathway may involve the upregulation of receptors AdipoR1 and AdipoR2 in dendritic cells of advanced breast cancer, leading to impaired T-cell immune response." (PMID 34876619, 2021). "AdipoR1/2 probably mediates this on TAMs, which is suggested by the observation that AdipoR1/2 expression on dendritic cells mediates T cell anergy and tolerance in breast cancer." (PMID 33391518, 2021). "Our overarching hypothesis was that higher IHC expression of LEP, LEPR, ADIPOQ, ADIPOR1, and ADIPOR2 within the breast tumor microenvironment is associated with breast cancer aggressiveness, but we generally observed the opposite." (PMID 32046756, 2020). "The molecular mechanisms underlying the association between increased adiposity and aggressive breast cancer phenotypes remain unclear, but likely involve the adipokines, leptin (LEP) and adiponectin (ADIPOQ), and their receptors (LEPR, ADIPOR1, ADIPOR2)." (PMID 32046756, 2020). "Adiponectin itself and AdipoR1 at the mammary tissue level may play important roles in the development of breast cancer." (PMID 32215366, 2019). "In addition, we reported protein expression levels of AdipoR1, AdipoR2 and adiponectin in the mammary tumor (MT), mammary fat pad (MFP) and liver tissues in relationship to serum adiponectin levels in this breast cancer mouse model." (PMID 32215366, 2019). "The reduction in the expression of AdipoR1 mRNA and the increase in the expression of AdipoR2 mRNA could indicate that the effective receptor for the in vivo signaling of adiponectin in breast cancer tissue is AdipoR1." (PMID 29311755, 2017). "Moreover, overexpressed miR-221/222 can promote the EMT in breast cancer by negatively regulating adiponectin receptor 1 (ADIPOR1)." (PMID 28261196, 2017).
breast carcinoma (continued). "In addition, miR-221/222 were negatively correlated with ADIPOR1 expression across breast cancer cell lines and tumors." (PMID 23776679, 2013). "The adiponectin receptors, AdipoR1 and AdipoR2, have been detected in human breast cancer specimens, but not clearly associated with other biomarkers." (PMID 21974986, 2011). "Based on their involvement in breast cancer and the availability of commercial antibodies, the ADIPOR1, ADORA1, BTG2 and CD46 genes were selected among the 27 previously identified genes to further investigate the association of protein expression levels to overall patient survival." (PMID 20553615, 2010). "However, it is worth mentioning that another event increasing the incidence of breast cancer may come from ADIPOQ and/or ADIPOR1 single nucleotide polymorphisms." (PMID 37240258, 2023). "Furthermore, miR-221 and miR-222 expression was negatively correlated with ADIPOR1 mRNA levels across breast cancer cell lines as well as tumors derived from breast cancer patients, suggesting that ADIPOR1 may be an endogenous target of miR-221/222." (PMID 23776679, 2013). "The results demonstrated that the expression levels of OLR1, ADIPOR1, CEACAM6, DNASE2, CD53, BMF, and CAMP were significantly elevated in breast cancer samples compared to healthy controls (p < 0.05)." (PMID 40282270, 2025). "We used immunohistochemistry (IHC) to assess LEP, LEPR, ADIPOQ, ADIPOR1, and ADIPOR2 expression in breast tumor tissue microarrays among a sample of 720 women recently diagnosed with breast cancer (540 of whom self-identified as Black)." (PMID 32046756, 2020). "Expression levels of adiponectin, AdipoR1 and AdipoR2 proteins were measured in the mammary fat pad (MFP), mammary tumor (MT) and liver tissues from 74 weeks old MMTV-TGF-α transgenic mice with and without MT using Western Blot." (PMID 32215366, 2019). "With regard to the expression of AdipoR1 and AdipoR2 mRNA in HCC1937 breast cancer cells, as in the case of MCF-7 cells, the expression of AdipoR2 mRNA (1.336 ± 0.905) was greater than the expression of AdipoR1 (1.181 ± 0.67)." (PMID 29311755, 2017). "In turn, a specific siRNA for IGF-1R prevents adiponectin-induced ERα transactivation, thus proving the existence of a functional interplay among adiponectin/AdipoR1, ERα, and IGF-1R, promoting ERα+ breast cancer cell growth." (PMID 29036907, 2017). "All these data address the existence of a possible cross-talk between Adiponectin/AdipoR1, ERα, and IGF-IR involved in the positive regulation of ERα-positive breast cancer cell growth." (PMID 26236690, 2015). "Emerging evidences address the existence of a cross-talk between adiponectin/AdipoR1 and IGF-IR in breast cancer." (PMID 26236690, 2015). "In this review, we discuss the cross-talk between adiponectin/AdipoR1 and IGF-I/IGF-IR in breast cancer." (PMID 26236690, 2015). "It has been demonstrated by several groups that human breast cancer cells including MDA-MB-231 and MCF-7 cells have detectable levels of adipoR1 and adipoR2 proteins." (PMID 23691032, 2013). "Immunohistochemical studies have shown that leptin, adiponectin and their receptors (Ob-R, AdipoR1 and AdipoR2) are detected in the cytoplasm of MCF-7 breast cancer cells." (PMID 23750285, 2013). "We stably transfected an ADIPOR1, Myc-DDK-tagged, construct into the basal-like breast cancer cell line MDA-MB-231, and generated a pool of polyclonal stable lines, in addition to a single clone isolated from the pool." (PMID 23776679, 2013). "In this study, we uncovered a unique relationship between miR-221/222, ADIPOR1, and EMT and provide further insight into miR-221/222-mediated EMT and breast cancer pathogenesis." (PMID 23776679, 2013). "We performed a case-control study on 733 breast cancer cases and 839 controls and genotyped 10 haplotype-tagging SNPs of adiponectin (ADIPOQ) and the type I adiponectin receptor (ADIPOR1) genes." (PMID 22295251, 2012).